STAG2 (STAG2 cohesin complex component)
Diseases named in the same sentence as STAG2 in open-access papers (continued):
Sharing a sentence is not in itself a finding about the gene and the disease.
prostate carcinoma (6 papers, 2013 to 2021). A carcinoma that arises from epithelial cells of the prostate gland. "This is similar to other recent studies of the STAG2 mutational hot spot region (corresponding to exon 9, 11, 12 and 20) in 90 acute leukemia samples and 225 adult carcinomas of various origin (colorectal-, gastric-, breast-, prostate carcinoma and non-small lung cell cancer)." (PMID 24088605, 2013). "Furthermore, miR-409-5p overexpression and inhibition in a prostate cancer cell line reduced or increased STAG2 mRNA or protein, respectively." (PMID 34707078, 2021). "Similarly, miR-154* was identified as a regulator of STAG2 in prostate cancer cells by the same research group." (PMID 34707078, 2021).
sarcoma (6 papers, 2017 to 2023). A usually aggressive malignant neoplasm of the soft tissue or bone. "To test this, we used SK-ES-1, a sarcoma cell line with a somatic homozygous point mutation in STAG2." (PMID 28430577, 2017). "In the present study, we hypothesize that loss of Stag2 cooperates with EWS-FLI1 in generating sarcomas derived from murine mesenchymal stem cells (MSCs)." (PMID 31898537, 2020). "Thus, we concluded that Stag2 knockdown had a synergistic effect with EWS-FLI1 in the production of sarcomas." (PMID 31898537, 2020). "The primary objective of the study is to determine whether Stag2 down-regulation might cooperate with EWS-FLI1 in the generation of sarcomas from MSCs." (PMID 31898537, 2020). "Loss of Stag2 has a synergistic effect with EWS-FLI1 in the production of sarcomas from murine MSCs, but the mechanism may not relate to increased proliferation or chromosomal instability." (PMID 31898537, 2020).
urothelial carcinoma (6 papers, 2014 to 2023). A malignant neoplasm derived from the transitional epithelium of the urinary tract (urinary bladder, ureter, urethra, or renal pelvis). "As the majority of available urothelial carcinoma (UC) cell lines are derived from invasive tumours, including the five STAG2 mutant cell lines for which stage and/or grade information is available, they are not representative of the spectrum of UC in general." (PMID 24270882, 2014).
colorectal cancer (5 papers, 2016 to 2023). A primary or metastatic malignant neoplasm that affects the colon or rectum. "However, impact of STAG2 mutation in colorectal cancer remains questionable." (PMID 37260182, 2023). "Consistent with the data from TCGA, we observed that high expression of STAG2 relates to the adverse outcome of patients with colorectal cancer." (PMID 37985839, 2023). "Within the confines of our study, a rigorous examination of STAG2 expression patterns among patients grappling with colorectal cancer yielded an observation of paramount importance: heightened STAG2 expression markedly correlates with diminished patient outcomes." (PMID 37985839, 2023).
glioma (4 papers, 2013 to 2021). A benign or malignant brain and spinal cord tumor that arises from glial cells (astrocytes, oligodendrocytes, ependymal cells). "Although STAG2 deficiency comprises only a small subset of gliomas, this case adds clinical evidence to existing preclinical data supporting a role for STAG2 mutations in gliomagenesis and resistance to standard therapies." (PMID 32528726, 2020). "For instance, we identified mutations in STAG2 as a high-confidence biomarker of poor prognosis in glioma, and we found that STAG2-mutant gliomas were exquisitely sensitive to treatment with the PARP inhibitor olaparib." (PMID 30526857, 2018). "Mutations in STAG2 are associated with sensitivity to the PARP inhibitor olaparib, while CDKN2A deletions are associated with sensitivity to the CDK4/6 inhibitor palbociclib in glioma cell lines." (PMID 30526857, 2018).
urothelial bladder cancer (4 papers, 2017 to 2026).
Cornelia de Lange syndrome (3 papers, 2018 to 2024). A rare syndrome characterized by low birth weight, delayed growth, intellectual disabillity, behavioral problems, and a distinctive facial appearance (thin, arched eyebrows, low set ears, small teeth, and small nose). "Mutations of cohesin subunits and regulators, including STAG2, cause the Cornelia de Lange syndrome (CdLS) and other similar developmental diseases, collectively termed cohesinopathy." (PMID 35959892, 2022). "Cohesinopathy in humans leads to diseases with cancer proneness, developmental malformation, and/or intellectual disability and behavioral issues, such as Cornelia de Lange syndrome or mutations in STAG1 or STAG2." (PMID 29943428, 2018). "Congenital variants in STAG2 have also been described in association with developmental disorders, most notably Mullegama–Klein–Martinez syndrome, X-linked holoprosencephaly-13, and Cornelia de Lange syndrome." (PMID 38279279, 2024). "Somatic mutations in the STAG2 sequence have been associated with various types of cancer, while congenital variants have been linked to developmental disorders such as Mullegama–Klein–Martinez syndrome, X-linked holoprosencephaly-13, and Cornelia de Lange syndrome." (PMID 38279279, 2024).
developmental delay (3 papers, 2019 to 2025). "Pathogenic variants in STAG2 have rarely been implicated in an X-linked cohesinopathy associated with undergrowth, developmental delay, and dysmorphic features." (PMID 36467423, 2022). "Here, we describe for the first time a mosaic STAG2 variant (c.2184=/G>T p.Gln728=/His) in an individual with developmental delay, microcephaly, and hemihypotrophy of the right side." (PMID 36467423, 2022). "Germline variants in STAG2 have been described to cause an X-linked cohesinopathy associated with growth retardation, developmental delay, and dysmorphic features, both in females and males." (PMID 36467423, 2022). "Together, our findings indicate that mosaic STAG2 variants should be considered as a cause of developmental delay, microcephaly, supernumerary nipples, and growth retardation and we expand the complex genotypic and phenotypic spectrum of cohesinopathies." (PMID 36467423, 2022). "Our clinical findings in line with previously published reports indicate that the STAG2-associated phenotype is dominated by global developmental delay, severe microcephaly, and brain abnormalities." (PMID 36467423, 2022). "Here, we describe for the first time a mosaic STAG2 variant in an individual with developmental delay, microcephaly, and hemihypotrophy of the right side." (PMID 36467423, 2022). "Our findings indicate that mosaic STAG2 variants should be considered as a cause of developmental delay, microcephaly, supernumerary nipples, and growth retardation, especially if features appear asymmetric or affect in particular one side of the body." (PMID 36467423, 2022). "In this study, we describe a mosaic STAG2 variant in an individual with developmental delay, microcephaly, epilepsy, ataxia, and hemihypotrophy of the right side." (PMID 36467423, 2022). "We now present the case of a 4‐year‐old male with developmental delay, failure to thrive, short stature, and polydactyly with a likely pathogenic STAG2 de novo missense hemizygous variant, c.3027A>T, p.Lys1009Asn." (PMID 30447054, 2019). "This case emphasizes that even de novo STAG2 truncating variants can produce markedly different organ-specific outcomes, from mild developmental delay to life-threatening cardiac malformations, highlighting the need for individualized clinical surveillance and long-term follow-up." (PMID 41300816, 2025). "In summary, most published STAG2 MKMS cases present with global developmental delay, microcephaly, hypotonia, and mild craniofacial dysmorphism." (PMID 41300816, 2025).
Intellectual disability (3 papers, 2017 to 2019). "Duplication of STAG2, which encodes a subunit of cohesin complex, was associated with intellectual disability and behavioral problems." (PMID 30532227, 2018). "This serves as convincing evidence for a causal relationship between the STAG2 p.Ser327Asn mutation and the phenotype of intellectual deficiency, short stature, and other abnormalities observed in our patients, thus defining a new cohesinopathy." (PMID 29263825, 2017). "The first reports of STAG2 copy number variants were identified in 33 males with chromosome Xq25 duplications, involving STAG2, with intellectual disability, behavioral problems, seizures, malar flatness, and prognathism." (PMID 30447054, 2019).
metastatic disease (3 papers, 2014 to 2022). "Excluding indeterminate cases, 26.9% and 22.2% of cases had STAG2 loss of expression among patients with localised and metastatic disease, respectively." (PMID 36221002, 2022). "Within the cohort of patients with metastatic disease, 21/30 (70.0%) had retained STAG2 expression, 6/30 (20.0%) had STAG2 loss of expression, and 3/30 (10.0%) had indeterminate staining." (PMID 36221002, 2022). "Crompton and colleagues showed that STAG2 mutation, resulting in a loss of expression, was associated with metastatic disease." (PMID 32225029, 2020). "Indeed, 88% of the patients of STAG2 loss in the primary tumor presented metastatic disease." (PMID 32225029, 2020). "In localised and metastatic disease, STAG2 was lost in 29/108 and 6/27 cases, respectively." (PMID 36221002, 2022). "Transposon-mediated disruption of STAG2 in a KRASG12D genetically engineered mouse model promotes the development of PDA and its progression to metastatic disease." (PMID 24484537, 2014).
myeloid leukemia (3 papers, 2016 to 2023). A clonal proliferation of myeloid cells and their precursors in the bone marrow, peripheral blood, and spleen. "These authors further showed that ectopic expression of wild-type STAG2 can lead to growth suppression of myeloid leukemia cells harboring specific endogenous mutations of STAG2." (PMID 26871722, 2016).
pancreatic cancer (3 papers, 2014 to 2020). "Multivariate Cox Regression analysis showed that STAG2 is an independent prognostic factor for survival in pancreatic cancer patients." (PMID 24484537, 2014).
trisomy 8 (3 papers, 2023 to 2026). "Conversely, the frequency of STAG2 mutations and trisomy 8 increased with age and appeared protective against early development of advanced MDS." (PMID 40664679, 2025).
anaemia (2 papers, 2015 to 2021). "In contrast to Tet2-only mutant mice, Tet2/Stag2-mutant mice developed leukocytosis, absolute monocytosis, anemia, and thrombocytopenia." (PMID 33351783, 2021).
bladder tumors (2 papers, 2014 to 2022). "The frequency of chimeric expression pattern found in bladder tumours suggests that intra-tumour genomic evolution commonly involves loss of STAG2, even in low-grade, low-stage tumours, which are generally considered to represent an evolutionarily stable sub-group." (PMID 24270882, 2014).
chronic myelogenous leukaemia (2 papers, 2020 to 2021). "We had previously shown that BET inhibition is effective in blocking precocious gene expression in the chronic myelogenous leukemia cell line K562 containing a STAG2 mutation." (PMID 33284104, 2020).
Failure to thrive (2 papers, 2019 to 2025). Failure to thrive (FTT) refers to a child whose physical growth is substantially below the norm. "Features such as short stature, failure to thrive, scoliosis, vertebral anomalies, and rib fusion have been documented, particularly in individuals with STAG2 variants, but are also observed in STAG1-related cases." (PMID 40361893, 2025).
Fanconi anemia (2 papers, 2020 to 2022). Fanconi anemia (FA) is a hereditary DNA repair disorder characterized by progressive pancytopenia with bone marrow failure, variable congenital malformations and predisposition to develop hematological or solid tumors. "KEGG pathway analysis showed that cell cycle, Fanconi anemia pathway, DNA replication, homologous recombination, progesterone-mediated oocyte maturation, oocyte meiosis, and cellular senescence were the most significantly altered pathways in the STAG2 high expression group (P-adjusted < 0.05)." (PMID 35371307, 2022).
heart defects (2 papers, 2025). "Congenital heart malformations are common in patients with STAG2-truncating variants, and two of our individuals presented with coarctation of the aorta." (PMID 41492387, 2025). "The diverse clinical spectrum of females with truncating STAG2 variants includes developmental delay, intellectual disability, and congenital abnormalities including congenital heart defects, brain malformations, skeletal defects, and craniofacial features like holoprosencephaly." (PMID 41492387, 2025). "This case broadens the phenotypic spectrum of STAG2-related cohesinopathy by illustrating that severe congenital heart malformations can represent the predominant neonatal manifestation, even before neurodevelopmental abnormalities emerge." (PMID 41300816, 2025).
holoprosencephaly (2 papers, 2022). Holoprosencephaly (HPE) is a complex brain malformation resulting from incomplete cleavage of the prosencephalon, occurring between the 18th and 28th day of gestation, and affecting both the forebrain and face, which results in neurological manifestations and facial anomalies of variable severity. "As for the second phenotype associated with variants of STAG2, i.e., HPEs, these are severe forms of lobar or semilobar holoprosencephaly with agenesis or dysgenesis of the corpus callosum." (PMID 35887945, 2022). "Therefore, our observations further support that loss-of-function variants in STAG2 seem to cause especially midline brain malformations, including holoprosencephaly, agenesis of the corpus callosum, and dysgenesis of the corpus callosum." (PMID 36467423, 2022). "Loss-of-function (LoF) STAG2 variants cause either holoprosencephaly (HPE) or Mullegama–Klein–Martinez syndrome (MKMS), are de novo, and only affect females, indicating male lethality." (PMID 35887945, 2022). "Importantly, cMRI images of both individuals with STAG2-associated cohesinopathy presented here showed profound brain anomalies, e.g., delayed and incomplete myelination, hypotrophy, thin and dysplastic corpus callosum, or semilobar holoprosencephaly." (PMID 36467423, 2022).
lung adenocarcinoma (2 papers, 2014 to 2023). A carcinoma that arises from the lung and is characterized by the presence of malignant glandular epithelial cells. "Only one splicing event was significantly associated with STAG2 mutation in lung adenocarcinoma and none in AML." (PMID 24498085, 2014). "As an additional control, we identified alternative splicing events significantly associated with STAG2 mutations in lung adenocarcinoma and AML, as STAG2 is not expected to be a splicing regulator and it is mutated at a similar frequency in both cancer types." (PMID 24498085, 2014). "In stomach adenocarcinoma (STAD), lung adenocarcinoma (LUAD), and colon adenocarcinoma (COAD), STAG2‐mutant tumors exhibited a trend of high KMT5A expression compared with STAG2WT tumors." (PMID 37985839, 2023).
neuroblastoma (2 papers, 2013 to 2016). Neuroblastoma (NB) is the most common solid, extracranial childhood tumor. "With the exception of Stag2, expression of all cohesin subunits increased during neuroblastoma progression, as in the case of Sgo1." (PMID 27539729, 2016). "As no STAG2 mutation was detected in this study, we conclude that inactivating mutation of STAG2 is not likely causative to neuroblastoma aneuploidy." (PMID 24088605, 2013).
osteosarcoma (2 papers, 2018 to 2025). A usually aggressive malignant bone-forming mesenchymal neoplasm, predominantly affecting adolescents and young adults. "This further is supported by in vitro work in osteosarcoma U2-OS cells, where loss of STAG2 is associated with decreased activation of the PI3K pathway, evidenced by decreased phosphorylation of PI3K, Akt, and mTOR." (PMID 40025053, 2025).
ovarian carcinoma (2 papers, 2020 to 2021). A malignant neoplasm originating from the surface ovarian epithelium. "We predict that STAG3 plays a role in ovarian cancer tumorigenesis, based on its gene fusions and upregulated expression, as well as the central role in cancer of the mitotic cohesin proteins STAG1 and STAG2, whose mutation or inactivation cause aneuploidy." (PMID 34215221, 2021).